ATR (ATR checkpoint kinase)
Diseases named in the same sentence as ATR in open-access papers (continued):
Sharing a sentence is not in itself a finding about the gene and the disease.
ovarian carcinoma (continued). "Other drugs acting on the same DNA damage response pathway, such as ATR inhibitors, have shown more promise in ovarian cancer, and are being investigated as potentiators of immune checkpoint blockade, which are otherwise often ineffective on their own." (PMID 41029436, 2025). "This is evidenced by increased levels of γH2AX and other DDR markers, such as ATM/ATR/CHK2/CHK1, thereby sensitizing ovarian cancer cells to ATR inhibitors." (PMID 39924521, 2025). "ADAR1 prevent the accumulation of R ring in ovarian cancer, avoid the DNA damage of cancer cells and the activation of ATR-Chk1 cell cycle checkpoint, so that the cell cycle of G1/G0 phase does not stall." (PMID 38343637, 2024). "REV1 is necessary for gap suppression and tolerance of DNA damage from both intrinsic sources and ATR/WEE1-inhibition in ovarian cancer cells." (PMID 38438348, 2024). "Another ATR inhibitor (M4344) in combination with PARPi (niraparib) is investigated in PARPi resistant ovarian cancer in a clinical trial (NCT04149145)." (PMID 38184614, 2024). "Inhibition of AXL (via bemcentinib or MYD1-72) resensitizes ovarian cancer cells to platinum, ATR inhibitors (ATRis) and PARPis by increasing DNA damage and inducing RS." (PMID 38539161, 2024). "Of particular significance, ATMIN (ATM-INteracting protein, also known as ASCIZ (ATM/ATR substrate Chk2-interacting Zn2+-finger protein)) was frequently deleted in bBRCA1 ovarian cancers, with a prevalence of 68%." (PMID 39198848, 2024). "More recently, CCNE1 amplification has been proposed as a potential biomarker indicative of response to combined WEE1 inhibition and ATR inhibition in preclinical ovarian cancer and endometrial cancer models." (PMID 37457127, 2023). "Combined inhibition of BRD4 with ATR/WEE1 is synergistic in ARID1A mutant clear cell ovarian cancer cells." (PMID 37841875, 2023). "In support, reduced levels of pSer428 ATR in the cytoplasm of advanced epithelial ovarian cancer cells are correlated with poor prognosis." (PMID 37511442, 2023). "CAPRI is a phase II clinical trial of olaparib in combination with the ATR inhibitor ceralasertib (AZD6738) in patients with recurrent ovarian cancer; data on the platinum-resistant ovarian cancer cohort of this trial has been published." (PMID 37457127, 2023). "NCT04149145 is a phase I trial of niraparib in combination with the ATR inhibitor M4344 among patients with PARPi-resistant, recurrent ovarian cancer and was anticipated to begin enrollment in December 2022 (NCT04149145)." (PMID 37457127, 2023). "The sensitization of several ovarian cancer cell lines to topotecan was demonstrated either by inhibition of ATR with VE-821 or depletion of ATR by RNAi." (PMID 37637936, 2023). "ATR inhibitors (ATRis), which target the ATR pathway, have also shown preliminary efficacy for the treatment of ovarian cancer (OC)." (PMID 36497387, 2022). "In several published clinical trials, patients with advanced bowel cancer and ovarian cancer benefited from ATR inhibitor therapy." (PMID 36204234, 2022). "In a recent report, inhibition of ataxia telangiectasia and Rad3-related checkpoint kinase 1 (ATR-Chk1) was shown to enhance oncolytic toxicity of adenovirus in ovarian cancer by using the small molecule inhibitor UCN-0134." (PMID 35948546, 2022). "HMGB3 deletion has been demonstrated to increase the cell sensitivity to cisplatin via the attenuation of ATR/CHK1/p-CHK1 DNA damage signaling pathway activation in ovarian cancer, suggesting an important role for HMGB3 in ovarian cancer." (PMID 35332131, 2022). "A recent study demonstrated that the targeted depletion of HMGB3 sensitizes chemoresistant ovarian cancer cells to cisplatin through the inhibition of the ATR/CHK1/p-CHK1 DNA damage signaling pathway." (PMID 35332131, 2022). "The novel ADAR1/R-loop/ATR axis is critical for ovarian cancer progression and a potential target for ovarian cancer therapy." (PMID 35711824, 2022).
ovarian carcinoma (continued). "For example, the VIOLETTE study (NCT03330847) in patients with mTNBC investigated the use of olaparib as 2/3L therapy, or combining olaparib with other molecular targeted drugs, such as ceralasertib (an ATR inhibitor), as has been proposed for ovarian cancer." (PMID 34467476, 2022). "Together, our results identify a novel ADAR1/R-loop/ATR axis critical for ovarian cancer progression and a potential target for ovarian cancer therapy." (PMID 35711824, 2022). "ATR is referred to as the “master of DDR”, highlighting the relevance of miRNAs implicated in DDR pathways as novel therapeutic targets for ovarian cancer." (PMID 34072593, 2021). "Ovarian cancer cells often carry BRCA1 or BRCA2 (BRCA1/2), germline or somatic mutations in ataxia telangiectasia and Rad3-related protein (ATR) or checkpoint kinase 1 (CHK1) genes of the homologous recombination (HR) pathway." (PMID 34072593, 2021). "Currently, several studies with selective ATR inhibitors are ongoing testing combinations with chemotherapy or PARP inhibitors in recurrent ovarian cancer patients." (PMID 35052761, 2021). "The overproduction of ROS activates the ATR-Chk1 axis, resulting in resistance to cisplatin in ovarian cancer cells, and the inhibition of ATR and Chk1 reverses chemotherapeutic resistance." (PMID 34405016, 2021). "In conclusion, the combined administration of ATR inhibitor and belotecan was shown to be synergistic in both the chemotherapy-resistant ovarian cancer preclinical model and the chemotherapy-sensitive model." (PMID 33513721, 2021). "Here we report a candidate biomarker of response to gemcitabine versus combined gemcitabine and ATR inhibitor therapy in HGSOC ovarian cancer." (PMID 34552099, 2021). "We have demonstrated that ATR inhibitor potentiated the activity of belotecan, which is one of the mainstay chemotherapies in recurrent ovarian cancer." (PMID 33513721, 2021). "The differential amplification in PIK3CA, MECOM, and ATR while interesting signals require validation using an orthogonal method and a larger cohort given the high degree of aneuploidy found in ovarian carcinoma." (PMID 33811746, 2021). "A randomized phase 2 study recently showed that the addition of ATR inhibitor berzosertib to gemcitabine improved PFS compared to gemcitabine alone in patients with ovarian cancer." (PMID 34552099, 2021). "The DUETTE trial (ClinicalTrials.gov Identifier: NCT04239014) is assessing the combination of ceralasertib (ATR inhibitor) and Olaparib in platinum-sensitive ovarian cancer previously treated with PARPi." (PMID 32854393, 2020). "In HGSOC cell lines, PARP inhibitors (e.g., olaparib) in combination with drugs targeting the ATR/CHK1 axis resulted in tumor regression in BRCA-mutant ovarian cancer." (PMID 32512900, 2020). "Inhibition of HMGB3 in cisplatin-resistant ovarian cancer cells resulted in transcriptional downregulation of ATR and CHK1, subsequently attenuating the ATR/CHK1/p-CHK1 DNA damage signalling pathway." (PMID 33187536, 2020). "HGSOC are known for their genome instability, a consequence of HRR deficiency found in about 50% of epithelial ovarian cancer, including those related to BRCA1/2 mutations or to mutations of other HRR genes such as ATM, ATR, RAD 51, PALB2." (PMID 32854393, 2020). "RNA interference (RNAi)-mediated depletion or inhibition of ATR has been shown to sensitize ovarian cancer cells to cisplatin, topotecan, gemcitabine, and the PARP inhibitor veliparib (ABT-888)." (PMID 31018854, 2019). "NU6027 was developed as a CDK2 inhibitor but its potentiation of cisplatin toxicity in breast and ovarian cancer cell lines led to its investigation as an inhibitor of ATR." (PMID 28448462, 2017). "In this regard, it is interesting that Aurora A kinase suppressed the expression of ATR in breast and ovarian cancer cells." (PMID 27398318, 2016).
ovarian carcinoma (continued). "No data on the association of these polymorphisms and response to therapy in ovarian cancer have been reported yet, while few data on the ATM, ATR, Chk1 and Chk2 SNPs under study have been reported in other tumor types." (PMID 27905519, 2016). "We here report the retrospective analysis of polymorphisms in 5 genes (ATM, ATR, Chk1, Chk2 and CDK12) involved in the cellular response to platinum in a cohort of 240 cancer patients with late stage ovarian cancer." (PMID 27905519, 2016). "NU6027 is a potent inhibitor of ATR activity in several breast and ovarian cancer cell lines, but its initial discovery as a CDK2 inhibitor renders it less interesting." (PMID 26610585, 2015). "In the current study, we investigated synthetic lethality in XRCC1 deficient and XRCC1 proficient Chinese Hamster ovary (CHO) and human ovarian cancer cells using ATR inhibitors (NU6027)." (PMID 23451157, 2013). "Our data provides evidence that ATR inhibition is suitable for synthetic lethality application and cisplatin chemopotentiation in XRCC1 deficient ovarian cancer cells." (PMID 23451157, 2013). "Our findings demonstrates that this synthetic targeted therapy, combining a novel liposomal formulation of VitC with an ATR inhibitor, not only enhances DNA damage and the cytotoxic efficacy of ceralasertib but also effectively drives ovarian cancer cells toward cell death." (PMID 41898493, 2026). "Parallel trials with other ATR inhibitors, including Ceralasertib, Elimusertib, Gartisertib, and M1774, have reported favorable tolerability and encouraging antitumor activity in triple-negative breast cancer, ovarian cancer, and non-small cell lung cancer." (PMID 41409249, 2025). "This meta-analysis suggests that ATR inhibitors show particularly favorable efficacy in patients with non-small cell lung cancer, while also demonstrating promising potential in the treatment of ovarian cancer." (PMID 41409249, 2025). "The presence of ADAR1 maintains normal dsRNA editing, prevents R ring accumulation in ovarian cancer, avoids cancer cell DNA damage and ATR-Chk1 cell cycle checkpoint activation, prevents G1/G0 phase cell cycle stagnation, and promotes the growth of cancer cells." (PMID 38343637, 2024). "This study revealed a new ADAR1/R-loop/ATR pathway that is crucial for ovarian cancer progression, and the exploration of ADAR1 inhibitors and ATR inhibitors may be a good direction for future treatment of ovarian cancer." (PMID 38343637, 2024). "The assumption that ATR inhibition would be effective in a state of increased replication stress can also be inferred from a previous clinical trial, wherein patients with ovarian cancer showed prolonged survival with ATR inhibition plus DNA damaging cytotoxic chemotherapy." (PMID 38827321, 2024). "ATR inhibition has been studied in ovarian cancer as a mechanism for overcoming PARPi resistance." (PMID 37457127, 2023). "In ovarian cancer, increased replication stress and DNA damage are prevalent, and inhibition of ATR may represent an effective strategy for ovarian cancer therapy." (PMID 35711824, 2022). "This study aimed to investigate whether previously identified determinants of sensitivity to ATR inhibition in non-ovarian cancers would act as predictive biomarkers in in vitro models of ovarian cancer, and to investigate novel determinants of sensitivity." (PMID 35954206, 2022). "The combination of helicase inhibitor with a PARP inhibitor (PARPi) or ATR inhibitor may overcome PARPi resistance in ovarian cancer." (PMID 35267530, 2022). "Interestingly, increased ATR/phospho-ATR expression is a poor prognostic factor in breast, bladder, and ovarian cancers." (PMID 34829691, 2021). "Furthermore, combination therapy with 673A and the DSB repair pathway inhibitors, AZD1390 (ATM) and AZD6738 (ATR), resulted in a synergistic killing ovarian cancer cell lines." (PMID 33664846, 2021).
ovarian carcinoma (continued). "Suppression of ATR by VE-821 (ATRi) can affect HR repair in ovarian cancer cells, leading to accumulation of DNA DSBs in cell nuclei, thereby increasing the sensitivity of ovarian cancer SKOV-3 cells to cisplatin." (PMID 33352723, 2020). "Indeed, this is supported by the significant correlation of the dephosphorylation status of cytoplasmic ATR (Ser428) with the severity of ovarian cancer in patients such as advanced stage, serous histology, large residual mass and so on." (PMID 32984322, 2020). "Combination treatment with olaparib and anticancer agents that disrupt HR repair such as ATR inhibitors (ATRi) or CHK1 inhibitors (CHK1i) may therefore represent an effective strategy to sensitize ovarian cancer cells to olaparib." (PMID 33352723, 2020). "The ATR inhibitor overcomes fork stabilization in BRCA-deficient cells by preventing RAD51 loading onto stalled forks and triggering MRE11-mediated fork degradation, as shown in PARP-resistant ovarian cancer cells and PDXs." (PMID 32029455, 2020). "Moreover, an ATR inhibitor further enhanced the killing of BRCA1-depleted ovarian cancer cells by cisplatin, topotecan, and veliparib." (PMID 31018854, 2019). "In clear contrast, dual ATM/ATR inhibition strongly potentiates the activity of both ETs against human cervical and ovarian carcinoma cells by efficiently blocking the formation of γ-H2AX, MDC1, BRCA1 and Rad51 foci following ET-exposure thereby resulting in extensive chromosome damage." (PMID 27029031, 2016). "Inhibitors of DNA repair enzymes including APE1, ATM, ATR, DNA-PK and PARP have been developed and the PARP inhibitor olaparib is the first-in-class approved in Europe and the USA for the treatment of advanced BRCA-mutated ovarian cancer." (PMID 26097887, 2015). "However, ATR was identified as the third highest scoring gene in a screen looking for synthetic lethal interactions with PARP inhibition and ATR inhibition sensitized ovarian cancer cells to the PARP inhibitor Veliparib." (PMID 25965342, 2015). "The present study does not support a major role for ATR mutations in hereditary susceptibility to breast and ovarian cancer." (PMID 15987455, 2005). "Altogether, the results demonstrated that the combination of a platinum-based chemotherapy agent with an ATR inhibitor improves therapeutic outcomes in an ovarian cancer model, and could represent a potential novel strategy for overcoming the clinical recurrence of ovarian cancer." (PMID 37633920, 2023). "Owing to its functional overlap with ATM, a DDR kinase already implicated in BC susceptibility, ATR has been previously tested as a potential candidate gene in two breast and ovarian cancer cohorts of respectively 126 and 54 patients without alterations of BRCA1/2." (PMID 36749285, 2023). "Whilst small molecule inhibitors of ATM and ATR are under clinical trial evaluation, Mre11 blockade could impair both ATM and ATR mediated pathways simultaneously and could be an effective strategy in ovarian cancers which frequently manifest genomic instability and replication stress." (PMID 35853939, 2022). "We hypothesized that the combination of olaparib with anticancer agents that disrupt HRR by targeting ataxia telangiectasia and Rad3-related protein (ATR) or checkpoint kinase 1 (CHK1) may be an effective strategy to reverse ovarian cancer resistance to olaparib." (PMID 33352723, 2020). "However, the results of the study suggest that ATR is not involved in hereditary susceptibility to breast and ovarian cancer." (PMID 15987455, 2005). "Previously, we found that HMGB3 facilitates transcription of the DNA damage response kinases, ATR and CHK1, in human ovarian cancer cells." (PMID 41009989, 2025). "This study investigated the combined effects of olaparib with ATR and CHK1 inhibitors (ATRi and CHK1i) on migration, invasion, and EMT-related protein expression and miRNA expression in ovarian cancer cell lines OV-90 and SKOV-3." (PMID 39859407, 2025).
ovarian carcinoma (continued). "The inhibition of HMGB3 in ovarian carcinoma cells that are resistant to cisplatin can result in the downregulation of ATR and CHK1 transcription, as well as the attenuation of the ATR/CHK1/p-CHK1 DNA damage signaling pathway." (PMID 38651153, 2024). "The potential for mechanistic synergism between ATR inhibitors (ATRi) and PARPis has been demonstrated in HRD and HRP ovarian cancer cells in preclinical models." (PMID 38894867, 2024). "ATR/ATM kinases, key molecules in DDR, are potential therapeutic targets for overcoming drug resistance in ovarian cancer." (PMID 38539161, 2024). "Two trials investigating combined ATR and PARP inhibition among patients with PARPi-resistant recurrent ovarian cancer are ongoing." (PMID 37457127, 2023). "In this review, we explore the preclinical rationale for the use of ATR inhibitors, CHK1 inhibitors, and WEE1 inhibitors, emphasizing their application to chemotherapy-resistant and PARPi-resistant ovarian cancer." (PMID 37457127, 2023). "A more potent ATR inhibitor, NU6027, was reported in 2011 and was demonstrated to sensitize several breast and ovarian cancer cell lines to IR (insulin resistance) and several chemotherapeutic agents." (PMID 37511442, 2023). "ATR and CHK1 inhibitors provoke premature mitotic entry and provide genomic instability to ovarian cancer cells." (PMID 35741017, 2022). "Other HRR pathway-related genes (ATM, ATR, CDK12, FANCA, FANCD2 and RAD50) were also found to play an essential role in ovarian cancer pathogenesis." (PMID 36729997, 2022). "The CAPRI trial is evaluating the ATR inhibitor, ceralasertib (AZD6738), in combination with olaparib, for platinum-sensitive or platinum-resistant recurrent ovarian cancer (NCT03462342)." (PMID 34976801, 2021). "Fitness genes identified in ovarian cancer cell lines also included many DDR transducers; among them, a critical role is played by ATR." (PMID 32512900, 2020). "Moreover, similar results were seen in models of BRCA-mutant ovarian cancer, suggesting that inhibition of ATR potentiates the effects PARP inhibition in BRCA-deficient cells, thus the combination of PARP and ATR inhibition may have benefits in other HDR-deficient cancers." (PMID 32183301, 2020). "As ATR is a master regulator of the DDR, this finding underscores the relevance of DDR as a new therapeutic target in ovarian cancer therapy." (PMID 32316968, 2020). "Because PARPi increases the reliance on ATR/CHK1 for genome stability, the combination of PARPi with ATR inhibition suppressed ovarian cancer cell growth independently of the efficacy of HRR." (PMID 33352723, 2020). "VE-821, another identified ATR inhibitor, sensitized OVCAR-8, SKOV-3 and PEO1 ovarian cancer cell lines to cisplatin, topotecan and veliparib." (PMID 32316968, 2020). "Following IR of human ovarian carcinoma cells, vanillin specifically affected NHEJ and was selective for DNA-PK over ATM and ATR." (PMID 26610585, 2015). "Nonetheless, because ATR changes have thus far been reported only in gastric and endometrial tumours exhibiting microsatellite instability, it is also possible that breast and/or ovarian cancer is not the primary cancer phenotype associated with germline mutations in this gene." (PMID 15987455, 2005). "Many clinical trials, including trials evaluating drugs targeting ATR, ATM, WEE1, checkpoint kinase 1/2 (CHK1/2), BRCA1/2 and RAD51, have been designed to evaluate interference with DDR pathways to overcome platinum and PARPi resistance in ovarian cancer." (PMID 38539161, 2024).